TET3 (tet methylcytosine dioxygenase 3)
Diseases named in the same sentence as TET3 in open-access papers (continued):
Sharing a sentence is not in itself a finding about the gene and the disease.
cancer (57 papers, 2012 to 2025). A tumor composed of atypical neoplastic, often pleomorphic cells that invade other tissues. "In summary, TET1 exhibited consistently low expression across various tumors, while TET3 showed highest expression levels, both closely associated with pan-cancer immune subtypes." (PMID 39104395, 2024). "We observed that TETs expression especially TET2 and TET3 was closely associated with AML among various human cancers." (PMID 32209730, 2020). "Mutations in FAT atypical cadherin 2 (FAT2), a gene associating with several cancers, and those in TET3, a member of the TET gene family, were identified in 3 and 2 cases, respectively." (PMID 28157189, 2017). "While TET2 mutations are thought to be driver mutations in haematopoietic malignancies, whole-exome sequencing of large cancer cohorts has revealed only rare mutations in TET1 or TET3 (refs 19, 48, 49)." (PMID 26607761, 2015). "In summary, TET1, TET2, and TET3 are required for maintenance of 5hmC at genes susceptible to hypermethylation in cancer." (PMID 24958354, 2014). "Collectively, it is implied that TET2 and TET3 could be involved in the differential regulation seen in cancers, however its exact association still needs to be explored further." (PMID 35372016, 2022). "TET3 postively correlated genes are specifically enriched in Hippo and neurotrophin signaling pathways, and organ morphogenesis, which contribute to developmental processes; all three TETs are linked to promoter 5fC/5caC levels at genes related to cancer pathways and stem-cell pluripotency." (PMID 29587824, 2018). "The results depicted in the Boxplot revealed that the expression level of the TET3 gene ranked highest across pan-cancer samples, followed by TET2, with TET1 exhibiting the lowest expression." (PMID 39104395, 2024). "In summary, studying TET3 in different cancers is highly relevant due to its potential as a therapeutic target." (PMID 39104395, 2024). "Following our comprehensive analysis spanning various cancer types, TET3 has emerged as a prime candidate for targeted therapeutic intervention." (PMID 39104395, 2024). "TET1 gene exhibited high methylation levels, whereas TET2 and TET3 genes displayed hypomethylation in most cancers, which correlated closely with patient prognosis." (PMID 39104395, 2024). "The expression pattern and clinical significance of TET3 have been determined in several human cancers, which indicated that it plays a different role between cancer occurrence and development." (PMID 36371552, 2023). "Whereas, several other investigations reported that TET3 was low-expressed in diverse human cancers as in cervical cancer, chronic lymphocytic leukemia cells and in colorectal cancer." (PMID 36371552, 2023). "Compared to other genes (TET1 and TET2) in the TET family, the functions of TET3 in human cancer remains limited." (PMID 35757739, 2022). "Results indicate that TET1 and TET3 gene and protein expression was cell-specific in cancer cell-lines." (PMID 35372016, 2022). "We identified 35 genes that were more frequently altered in HS/CB tumors versus corresponding TCGA cohorts; of which, 8 genes (PREX2, BIRC6, CNTNAP2, PTPRB, GRM3, ANKRD11, BRCA2, and TET3) are listed on the OncoKB Cancer Genes catalogue." (PMID 34446728, 2021). "As eraser regulators in 5mC methylation, ten-eleven translocation enzymes (TET1, TET2, and TET3) are often downregulated in cancer-inducing DNA demethylation by converting 5mC to 5-hydroxymethylcytosine (5hmC)." (PMID 33195409, 2020). "Among epigenetic genes, DNA methylation related epigenetic modifiers, DNMT1, DNMT3A, MBD1, MBD4, TET1, TET2, and TET3, have been studied related to cancer." (PMID 32093698, 2020). "In this paper, we investigated the effect of mutations on DNA methylation modification genes such as DNMT1, DNMT3A, MBD1, MBD4, TET1, TET2, and TET3 through a pan-cancer analysis." (PMID 32093698, 2020).
cancer (continued). "All these results further indicated that the role of TET3 in diverse human cancers was specific among different cancer types." (PMID 32209730, 2020). "In particular, TET3-dependent demethylation of transposable elements is specifically involved in epigenetic reprogramming, such as observed in cancer initiation." (PMID 32708659, 2020). "The expression pattern and clinical significance of TET3 have been determined in several human cancers." (PMID 32209730, 2020). "In summary, this study used bioinformatics analyses by different database and revealed that TET3 is correlated with cancer progression, prognosis." (PMID 31656201, 2019). "Then we identified the regulatory mechanism of genes by STRING, and determined if the CNAs of TET3 were correlated with cancer pathological status based on cBioPortal." (PMID 31656201, 2019). "Apart from the upregulation of TET2 and TET3, we also found that there is a significant downregulation of both DNMT3a and DNMT3b expression in cancer tissue compared with normal tissues." (PMID 29983831, 2018). "TET3 is rarely mutated in human cancers, but loss of TET function—as judged by low 5hmC levels—is frequently observed in many types of cancers." (PMID 28408905, 2017). "So far, although TET3 has been considered to be the most important regulator, relationships between TET3 and cancer have been poorly investigated." (PMID 27129173, 2016). "This study represents the first comprehensive genome-wide analysis of the role of TET1, TET2, and TET3 in patterning the distribution of 5mC and 5hmC in human cancer cells." (PMID 24958354, 2014). "Although this observation is purely correlative, it is consistent with the view that TET3 overexpression in cancer contributes to reprogramming of cancer cells via active DNA demethylation." (PMID 22346766, 2012). "Firstly, utilizing transcriptome data from 33 tumors available in the UCSC Xena database, we conducted an extraction and analysis of the expression profiles of the target genes belonging to the TET family (specifically, TET1, TET2, and TET3) across various types of cancer." (PMID 39104395, 2024). "Furthermore, the finding that TET3 genes display hypomethylation in most cancers, which correlates closely with patient prognosis, highlights its potential involvement in cancer progression and metastasis." (PMID 39104395, 2024). "TET3 is a member of the DNA demethylation modifying enzyme family and has been reported to be involved in gene regulation, repression of repetitive sequences and cancer development." (PMID 37718440, 2023). "Increased TET3 protein expression in cancer, could potentially indicate its involvement in abnormal stem cell regulation, contributing to progression, invasiveness and metastasis." (PMID 35372016, 2022). "Possible reason was that TET3 expression may play a different role between cancer occurrence and development, and further functional studies are needed to explore the underlying mechanism in AML development." (PMID 32209730, 2020). "Therefore, we investigated the effect of mutations on DNA methylation modification genes such as DNMT1, DNMT3A, MBD1, MBD4, TET1, TET2 and TET3 through a pan-cancer analysis." (PMID 32093698, 2020). "Furthermore, we evaluated the prognostic value of TET3 at mRNA level by Kaplan-Meier plotter analysis tool with cases enrolled from multiple GEO datasets and TCGA (the cancer genome atlas)." (PMID 31656201, 2019). "TET3 is demethylase and related to epigenetic modification, so TET3 might be a good target for cancer treatment." (PMID 31656201, 2019). "Furthermore, the results also demonstrated that hypoxia-induced TET1/TET3 proteins made a great contribution to the activation of the TNFα- p38-MAPK pathway in regulating cancer stemness." (PMID 26869355, 2016). "This heterogeneity suggests that TET3 may play distinct roles in different cancer subtypes." (PMID 39104395, 2024).
cancer (continued). "Further studies on this model may explain the role of TET3 in glia genesis and cancer and shed light on whether the amount of TET3 expressed, and/or cell-specific expression, might be key factors in restoring some of the functional defects observed in dTet-deficient flies." (PMID 35396259, 2022). "In some cancer cells Dppa3 could also mediate demethylation by preventing Tet3 function." (PMID 35477484, 2022). "Critically, the identification of the TET family, specifically TET3, as an invaluable regulator of the inflammatory response in the colon, provides the cornerstone to empirically connecting the health of the commensal bacteria residing in the gut to the development of cancer." (PMID 32708659, 2020). "TET3 is the demethylase and may regulate cancer progression in the epigenetic level." (PMID 31656201, 2019). "Moreover, in the quantitative methylation-specific PCR (Q-MSP) analysis, the normalized methylation value (NMV) for the TET1 and TET3 gene promoters tended to be higher in cancer cells than in normal tonsil samples and normal cell lines (P < 0.001 and P = 0.002, respectively)." (PMID 29849955, 2018). "This study yields a comprehensive genome-wide view of TET-targeted loci in human cancer cells, revealing for the first time loci that are particularly susceptible to TET-regulated cytosine modifications and identification of distinct and overlapping functions of TET1, TET2, and TET3." (PMID 24958354, 2014). "The expression of TET1, TET2, and TET3 positively correlated in pan-cancer, with a stronger positive correlation observed between TET2 and TET3." (PMID 39104395, 2024). "To investigate the expression of TET3 and AHR in cancer, we conducted an analysis using the TCGA database." (PMID 37718440, 2023). "To further explore the effect of TET3 on the maintenance of stem cell-like characteristics in ESCC cells, we examined the expression of candidate cancer stem cell (CSC) markers." (PMID 36518116, 2022). "In this study, the expression of TET3 in PTC and its relationship with the biological behavior of cancer cells were discussed for the first time." (PMID 35755313, 2022). "By assembling the Cancer Cell Line Encyclopedia (CCLE), we found that TETs expression especially TET2 and TET3 was highly expressed in AML cell lines among 40 types of human cancer cell lines." (PMID 32209730, 2020). "We will further investigate the expression of TET3 and TDG in cancer and their effects on gene expression profiles in subsequent studies." (PMID 32637580, 2020). "Despite the negative correlation between TET family genes expression and methylation levels in pan-cancer, unique patterns were observed, such as high methylation of TET1 in most analyzed cancers (except LIHC) and low methylation of TET2 and TET3 in most tumors." (PMID 39104395, 2024). "DNA methylation or demethylation in cancer is regulated by DNA methyltransferases (DMNTs), which include DMNT1, DMNT3A, and DMNT3B, and the ten-eleven translocation (TET) enzymes TET1, TET2, and TET3, which are known for their roles in cancer." (PMID 38566132, 2024). "In the field of cancer research, Cui and colleagues disclosed that down-regulation of TLX could induce TET3 expression and inhibit glioblastoma stem cells’ self-renewal and tumorigenesis." (PMID 32014008, 2020). "Coordination of these deregulated miRNAs may together lead to transcriptional deregulation in cancer via a large network, in which KAT6A and TET3 may also participate." (PMID 29587824, 2018). "Tet2/3fl/flFoxp3Cre mice lacking Tet2 and Tet3 in Treg cells develop inflammatory disease, and Treg cells from these mice show altered expression of Treg signature genes and upregulation of genes involved in cell cycle, DNA damage and cancer." (PMID 31043609, 2019). "So far, a direct correlation between TET3 and cancer has not been reported." (PMID 26869355, 2016).
cancer (continued). "A recent study demonstrated that the low level of 5-hmC observed in carcinoma in situ cells (CIS) of the testis corresponded to the absence of expression of TETs in these cells, especially TET3." (PMID 27129173, 2016).
infection (10 papers, 2016 to 2025). The state of being infected such as from the introduction of a foreign agent such as serum, vaccine, antigenic substance or organism. "Compared with Ad-GFP–infected cells, Ad-TET3 infection significantly enhanced TET3, STAT3, and H3K4me3 occupancy at the TGFB1 promoter." (PMID 40794443, 2025). "We then applied qRT-PCR to test the transcriptional level of a CMV coat protein (CP) which reflected the infection efficiency of CMV in tet3 mutants, overexpression of TET3 intact protein and TET3 variants." (PMID 35310653, 2022). "In human chondrocytes, TET1 and TET3 mRNA level were increased by Ad-TWIST1 infection by approximately 2 fold." (PMID 28220902, 2017). "Other epigenetic modulators like DNA demethylases TET2 and TET3, histone variant genes, INO80 complex, PRC2 complex genes, EED and SUZ12 were also associated with DNA methylation changes upon infection." (PMID 27112593, 2016). "Tet3-deficient T cells were also impaired in their ability to populate the SG and LP at day 21 and showed an early defect in differentiation with reduced CD69 and CD103 expression on day 7 of infection compared to control IEL and LP T cells." (PMID 36156073, 2022). "In EBi3-/- mice, infection caused an increase in DNA demethylation and analyzing EBi3-/-C versus EBi3-/-I we can see that TET1 plays the major differences observed in S2, but TET2 and TET3 also increased strongly their expression values." (PMID 32078636, 2020). "Removal of Tet2 and Tet3 by infection with AAV8-cre at 3 weeks was able to inhibit demethylation at these sites, but regions that had already undergone demethylation prior to AAV8-cre administration remained largely hypomethylated in these animals (<6% increase)." (PMID 29795194, 2018). "To test the role of Tet1/3 in CD8 effector T-cell fates during acute LCMV-Armstrong infection, we challenged RorcCreTg Tet1/3fl/fl mice (hereafter referred to as Tet1/3cDKO), in which double-positive thymocytes and their αβ CD4+ and CD8+ single positive progenies are deficient in Tet1 and Tet3." (PMID 40175595, 2025). "Since TET3 knockdown in macrophages does not affect TET2 expression, macrophage TET3 knockdown will probably not negatively affect the host’s defense against infections." (PMID 40794443, 2025). "Furthermore, the qRT-PCR analysis demonstrated a significant upregulation of TET1 but not TET2 and TET3 mRNA expression in normal gastric epithelium and GC cells after H. pylori (26695 and SS1) infection (P < 0.0001)." (PMID 37016382, 2023).
hematological malignancies (5 papers, 2019 to 2023). "Although genes encoding TET1 and TET3 are rarely mutated in hematopoietic diseases, TET2 frequently undergoes somatic mutation, affecting both lymphoid and myeloid lineages." (PMID 36675240, 2023). "Indeed, the reduction of TET2 and TET3 expression is responsible for hematologic disorders/malignancies and for increasing cytokine production." (PMID 35581740, 2022). "Notably, in an assay to quantify 5hmC in the genome of patients with various hematologic malignancies, levels of 5hmC in a significant proportion of patients with wild-type (WT) TET2 (and also WT TET1 and TET3) were as low as those from patients with TET2 mutations." (PMID 36675240, 2023).
blood cancer (2 papers, 2022 to 2023). "Establishing new mouse models, to delete Tet genes at various developmental stages and at specific T cell subsets will shed light on the precise biological roles of TET2 and TET3 in immune response and blood cancer development." (PMID 35990681, 2022). "Given that most patients with hematologic neoplasms are TET2 haplodeficient and that TET1 and TET3 mutations are rare, it is likely that activating the residual TET2 or the other TET family members TET1 and TET3 may be a promising treatment strategy for TET2-deficient malignancies." (PMID 36979633, 2023).
cardiovascular diseases (1 paper, 2025). "Second, although the disruption of 5‐hmC signaling through TET3 knockdown attenuated the PQ‐induced upregulation of gene expression in pathways associated with cardiovascular disease, we could not individually resolve their 5‐hmC modifications." (PMID 40547942, 2025).
Mendelian diseases (1 paper, 2022). "Apart from KMT2A, three other CXXC-domain-containing epigenetic regulators have been linked to Mendelian diseases: KMT2B (DYS28; OMIM:617284), DNMT1 (HSN1E; OMIM:614116), and TET3 (BEFAHRS; OMIM:618798)." (PMID 35727845, 2022).
neurodegenerative disease (1 paper, 2024). A disorder of the central nervous system characterized by gradual and progressive loss of neural tissue and neurologic function. "TET3, specifically, has been shown to play crucial roles in cognitive brain function such as memory and learning (potentially in a sex-specific manner) and therefore presents as a potential therapeutic target in the treatment of neurodegenerative disease." (PMID 38227585, 2024). "Mitochondrial dysfunction is considered to be the key and common factor for the pathologies of (age-related) neurodegenerative diseases and the TET proteins, including TET3, together with the epigenetic mark that they generate (5hmC) play significant roles in the development of these diseases." (PMID 38227585, 2024).
retinopathies (1 paper, 2025). "Overall, our findings build upon existing evidence supporting the crucial role of epigenetic mechanisms in the limited regenerative capacity of mammalian Müller glia and may offer new therapeutic targets, such as Tet3, for a range of retinopathies." (PMID 40747242, 2025).
TET3 also shares sentences with these, for which no sentence is quoted: autism (2 papers); chronic kidney disease (2); development delay (2); head and neck squamous cell carcinoma (2); laryngeal carcinoma (2); lymphoma (2); metabolic disease (2); neurodevelopmental disorder (2); Ureteral obstruction (2); acute coronary syndrome (1); acute lymphoblastic leukemia (1); acute myocardial infarction (1); adult T-cell leukemia (1); allergic asthma (1); amnesia (1); Anorexia (1); aplastic anemia (1); Ataxia (1); ataxia telangiectasia (1); autoimmunity disease (1); autosomal dominant cerebellar ataxia (1); B-cell acute lymphoblastic leukemia (1); bladder cancer (1); cardiomyopathy (1); Cerebral ischemia (1); cervical cancer (1); cervical squamous cell carcinoma (1); chronic hepatitis (1); chronic hepatitis B (1); cognitive deficits (1).
A further 35 diseases each share a sentence with TET3 in 1 paper.